ENG (endoglin)
Diseases named in the same sentence as ENG in open-access papers (continued):
Sharing a sentence is not in itself a finding about the gene and the disease.
tumor (continued). "Downregulation of ENG plays a crucial role in RSVL-promoted tumor microvessel growth, which leads to increased blood perfusion and drug delivery into tumor, thereby resulting in an enhanced anticancer effect of GEM." (PMID 32326402, 2020). "RSVL suppressed the expression of endoglin (ENG) and increased tumor microvessel growth and blood perfusion into tumor." (PMID 32326402, 2020). "We prepared bispecific liposomes encapsulated with a high concentration of a self-quenching NIRF dye, DY-676-COOH and endowed them with targeting antibody fragments directed towards the universal tumor markers FAP and endoglin." (PMID 32316521, 2020). "Strikingly, although clear anti-tumor effects in syngeneic mouse models have been shown, the binding affinity of TRC105 for mouse endoglin is significantly lower compared to human endoglin." (PMID 33375670, 2020). "This substantiates the selectivity of the Bi-FAP/mEnd-IL for its designated targets, namely murine endoglin on tumor endothelium and murine FAP on the tumor myofibroblasts and pericytes within this tumor model." (PMID 32316521, 2020). "Endoglin (ENG, CD105), an auxiliary receptor for several TGF-β superfamily ligands, is constitutively expressed in tumor microvessels." (PMID 29484142, 2018). "In summary, the research on endoglin role in mechanisms of angiogenesis in HCC proves that, similar to many other tumours, this marker is one of the most optimal markers of neovascularization." (PMID 30563158, 2018). "The cells that produce endoglin in vivo in HCC are, therefore, activated (proliferating) ECs, otherwise called tumour endothelial cells (TECs)." (PMID 30563158, 2018). "Blood vessels feeding the tumor were identified by means of CD34 and Endoglin (CD-105) expression, demonstrating strong positivity for CD34 in all the endothelial cells, whereas CD 105 marked a smaller number of blood vessels." (PMID 28390134, 2017). "These proteins comprised have previously been demonstrated to be present on tumor endothelium and have been used as targets of tumor endothelium vaccination: VEGFR2, TEM-1, Endoglin, ROBO, FGF-R2, and EGF-R." (PMID 28404894, 2017). "Endoglin (CD105) is an accessory component of the TGF-β receptor complex, which is expressed in a number of tissues and over-expressed in the endothelial cells of tumor neovasculature." (PMID 27294959, 2016). "CD105 (Endoglin/ENG), a co-receptor for transforming growth factor-beta (TGF-β), is involved in angiogenesis, particularly tumor angiogenesis." (PMID 27786256, 2016). "Of the fifty-five angiogenic factors evaluated, about half including angiogenin, endoglin and most specifically VEGF, a prime HIF-1α regulated growth factor, were down regulated in the shhnRNP A18 tumor as compared to control." (PMID 26824423, 2016). "Deficiency for BMP9 was accompanied by reduced growth of the primary tumor, in agreement with blockade of ALK1 signaling, combined with enhanced metastatic colonization, suggesting impairment of signaling via endoglin." (PMID 27741515, 2016). "In our recent study, we were the first to demonstrate that silencing endoglin with GET, using plasmid with constitutive promoter (CON plasmid), has pronounced antitumor efficacy in murine tumor model." (PMID 25909447, 2015). "A recent report proposed an intriguing interaction between endoglin and HGF, showing that soluble endoglin inhibited baseline and HGF stimulated Met signalling, impairing proliferation, migration and invasion of spindle cells, in mouse tumour model." (PMID 26296972, 2015). "For example, Endoglin (CD105) is required for endothelial cell proliferation and is currently used as a tool to measure tumour angiogenesis." (PMID 25889571, 2015).
tumor (continued). "One subsequent study focused on a member of the TGF-β receptor complex, endoglin (CD105), which is highly expressed on the vascular endothelium of tumors and believed to play a role in tumor neovascularization." (PMID 24860789, 2014). "Endoglin/CD105 is expressed on vascular ECs, hematopoietic cells and on several different normal and tumor cell types." (PMID 24632811, 2014). "Rac1 is Rho GTPase involved in VEGF signaling pathway, while endoglin is a TGF-β co-receptor and its expression is highly elevated in tumor blood vessels." (PMID 23593103, 2013). "Over-expression of both endoglin and ALK-1 is seen during tumour development and endothelial cell proliferation where new vessels are formed to support tumour growth." (PMID 24354965, 2013). "Endoglin expression in HMEC-1 human endothelial cells, 2H11 murine endothelial cells, TS/A tumor cells and TS/A subcutaneous tumors from BALB/c mice was determined with quantitative real time polymerase chain reaction (qRT-PCR)." (PMID 23593103, 2013). "Several studies propose CD105 or endoglin (receptor for TGF-β), a new marker which seems to be more specific to new tumour vessel." (PMID 24073397, 2013). "The expression of endoglin in the endothelial cells and expression of TGF-β in the tumor cells were significantly inhibited by toxicarioside A treatment." (PMID 23209720, 2012). "In summary, our results indicate that toxicarioside A can suppress tumor growth and tumor angiogenesis by attenuating the endoglin expression in endothelial cells and TGF-β in tumor cells." (PMID 23209720, 2012). "The attenuated expression of endoglin and TGF-β together further induce inhibition of cascade activation of ALK1 (Smad1/5/8) in endothelial cells, resulting in decreased tumor angiogenesis and suppression of tumor growth." (PMID 23209720, 2012). "In the present study, we found that toxicarioside A inhibited endoglin expression mainly in HUVECs and inhibited TGF-β expression in tumor cells, which lead to suppress tumor growth through inhibition of tumor angiogenesis." (PMID 23209720, 2012). "Endoglin (CD105) is predominantly expressed on cellular lineages within the vascular system and is highly expressed on endothelial cells during tumor angiogenesis and inflammation." (PMID 19759912, 2009). "In other studies, however, while angiogenic markers, including endoglin, positively correlate with tumor size, the presence of metastases, and a more advanced tumor stage, VEGF does not." (PMID 40565098, 2025). "Thus, we aimed to elucidate the roles of ENG expression in regulating TGF‐β signaling and tumor‐ and metastasis‐promoting traits in myCAFs." (PMID 40644310, 2025). "As an example, a subpopulation of stromal cells that did not express CD105 (endoglin, a cell surface protein) instructed dendritic cells and T lymphocytes to suppress tumor growth." (PMID 40592236, 2025). "Specifically, it showed a positive correlation between ENG expressions and immune lymphocytes, immunoinhibitors, immunostimulators, major histocompatibility complex (MHC) molecules, immuno-chemokines, or immuno-receptors across most tumor types." (PMID 39247590, 2024). "The presence of endoglin within the tumor microenvironment which expressed by neoplastic and non-neoplastic cells has opened a perspective for therapeutic purposes." (PMID 39552710, 2024). "Therefore, we further segregated ECs into tumor ECs (TECs) and normal ECs (NECs) using the TEC marker genes ENG, INSR, PECAM1, and SPRY1." (PMID 38182557, 2024). "Compared with normal ECs, tumor-associated ECs display higher expression of the stem cell marker CD34 and the angiogenesis promoting markers CD61 (Integrin b3) and CD105 (Endoglin), and lower or absent expression of von Willebrand factor (vWF)." (PMID 38426109, 2024). "Interestingly, SUM102-MerTKC2 ENG knockout clone 8 (SUM102-MerTKC2-crENG8) exhibited similar migration (~2.8-fold) and tumor growth patterns to SUM102-MerTKC2." (PMID 38791148, 2024).
tumor (continued). "To test this hypothesis, we knocked out ENG in the SUM102-MerTKC2 clone via ribonucleoprotein (RNP)-mediated CRISPR technology and examined the cell migration and tumor growth of the resulting knockout clones (SUM102-MerTKC2-crENG)." (PMID 38791148, 2024). "Among the non-immune cells, apart from a small population of tumor-associated endothelial cells (21 cells, 0.07% of the total cells, marked with VWF and ENG), the rest were cancer cells (11,228 cells, 35.46% of the total cells, marked with GPC3 and ASS1)." (PMID 38169544, 2024). "Notably, these markers have previously been linked to different cell types, including endothelial cells (CD44, ENG, F3, MCAM, and ITGB1), immune cells (CD14, CD44, CSPG4, ENG, HLA-DR/DP/DQ), and neuronal cells (NCAM1), as well as astrocytes and tumor cells." (PMID 39594703, 2024). "Endoglin was almost exclusively expressed on endothelial cell surface, without any staining of tumor parenchymal cells." (PMID 36844233, 2023). "ENG is a type I transmembrane glycoprotein, part of the transforming growth factor beta (TGF-β) receptor complex and is primarily expressed with activated endothelial cells playing a major role in angiogenesis both in development and tumor progression." (PMID 37432876, 2023). "In this previous work, endoglin expressing RCC cells showed increased tumorigenicity in mice when compared to endoglin negative tumor cells." (PMID 37396898, 2023). "The possible explanation of RES-induced tumor microvessel growth was given in the HCC827-HUVEC co-culture model where the activation of the ERK signaling pathway was observed and connected with a lower ENG expression level." (PMID 37175156, 2023). "Schimming and Marme examined endoglin in the tumor tissue of oral cancer at different TNM stages and in the normal mucosa." (PMID 36844233, 2023). "We observed that individual cells in the tumor islands show high endoglin expression, while the majority of the SCC cells do not." (PMID 37396898, 2023). "Targeting PDGF receptor signaling, FGF1/FGFR3, FAK pathway, HGF secretion, endoglin, activin A, Wnt2 and fatty acid oxidation, matrix metalloprotease 9 (MMP9) and hedgehog (Hh) signaling could delay tumor growth." (PMID 36139552, 2022). "The fact that endoglin is expressed by neoplastic and non-neoplastic cells within the tumor microenvironment suggests new possibilities for targeted therapies." (PMID 33804796, 2021). "Tissue sections of newly diagnosed and recurrent tumor of the same patient for two patients were compared and showed no change of endoglin levels upon recurrence." (PMID 33471197, 2021). "No relevant differences were observed between low and high endoglin-expressing tumors, neither for the analysis of tumor cell expression (p = 0.772), nor for endothelial expression (p = 0.891)." (PMID 33471197, 2021). "Moreover, in nearly 100% of cases their endothelial cells expressed CD105 (endoglin), a type III transforming growth factor (TGF) receptor and marker of activated endothelial cells in tumour-induced neovascularisation." (PMID 34282761, 2021). "VEGF and Endoglin gene expressions were higher in tumor tissue than in surrounding non-tumoral tissue for both types of cancer." (PMID 32434528, 2020). "In CRC cells, aberrant expression of E-cadherin/β-catenin complex can be observed as well as that of other angiogenesis markers such as Syndecan-1, platelet (Endothelial) cell adhesion molecule 1 [P(E)CAM-1, CD31], and endoglin (CD105), all involved in tumor progression and prognosis." (PMID 33276489, 2020). "Instead, we propose a second model in which the lack of downregulation of endoglin levels in the tumor endothelium after angiogenesis leads to the lack of stabilization and increased impairment of the function of tumor vessels." (PMID 31897911, 2020).
tumor (continued). "Thus, we expected the Bi-FAP/mEnd-IL to simultaneously target the tumor cells (based on human FAP), TAFs (based on murine FAP of host mouse), tumor vasculature (based on murine endoglin) and TAMs (based on phagocytic uptake)." (PMID 32316521, 2020). "Endoglin and VEGF are proteins with a major role in the tumor angiogenesis process." (PMID 32434528, 2020). "Given the considerable crosstalk between endoglin and VEGF pathways targeting both angiogenic pathways simultaneously was expected to exert more potent anti-angiogenic and therefore anti-tumor effects." (PMID 33375670, 2020). "Moreover, synergistic anti-tumor effects and complete regression of established MCF-7 human breast tumor nodules in mice were observed when endoglin antibodies were combined with chemotherapy." (PMID 33375670, 2020). "In this regard, the Bis-FAP/End-IL should accumulate in both tumor models based on binding to murine FAP expressing stromal cells such as myofibroblasts and pericytes and also to the murine endoglin expressing endothelial cells that make up the tumor vasculature." (PMID 32316521, 2020). "In RC, when sEng levels were low, there was predominant and specific staining of Endoglin in the tubule membrane (or Lieberkühn’s tubular vaults) of non-tumoral areas and to a lesser extent in the tumor stroma." (PMID 32434528, 2020). "Endoglin was chosen as a target for anti-angiogenic therapy, based on the observations of overexpression of this glycoprotein mainly in the newly sprouted tumour blood vessels, and not in the healthy vessels in the rest of the organ." (PMID 30563158, 2018). "Several clinical trials targeting ALK1 or its co-receptor endoglin are ongoing although the role of these two receptors in a tumor context are not yet understood and, so far present limited beneficial results." (PMID 30165893, 2018). "It is generally thought that endoglin (CD105) rather than CD34 is expressed in the vascular endothelium of tumor vessels forming de novo." (PMID 29748768, 2018). "As expected, NB5t primary cells showed increased expression of mesenchymal genes (NT5E, ENG, ACTA2, MME, CD44, VIM or ALPL), while NB5t tumor sample expressed mostly neuronal genes (TH, ENO2, NCAM1, DDC or CHGB) reflecting the neuroblastic phenotype of stage 4/M NB tumors." (PMID 29163787, 2017). "Consistent with this, we demonstrate that supplementation with NC derived stromal cells promotes proliferation and tumor aggressiveness in vivo, increasing expression of mesenchymal genes such as CD44, S100A10, ENG, VIM and ACTA2 (SMA), being the last one a typical marker of CAFs." (PMID 29163787, 2017). "In addition to blocking VEGFR2, YLL545 altered the expression of other molecules involved in tumor angiogenesis, including ITGAV, ENG, THBS1, FN1, and TEK." (PMID 27203384, 2016). "To further evaluate vascular targeted and antitumor effects in vivo, we used murine mammary carcinoma TS/A, in which the tumor cells do not express endoglin and ET." (PMID 25909447, 2015). "Endoglin (CD105) is a type III TGF-β coreceptor and it is overexpressed on tumor neovasculature." (PMID 26089870, 2015). "Endoglin acts in concert with FAK and PI3K signaling to maintain in vitro plastic phenotype and invasiveness (colony- and spheroid-forming ability) as well as in vitro and in vivo growth of tumor cells, which result in poor prognosis." (PMID 26210994, 2015). "In our previous study, in an endoglin non-expressing TS/A adenocarcinoma tumor model, the anti-tumor effect of pU6-antiCD105 plasmid was evaluated with the aim of demonstrating the anti-vascular effect of endoglin silencing." (PMID 26712792, 2015). "Since endoglin, like ALK1, binds to BMP-9 and -10, a soluble form of this protein, coupled to an Fc-domain was used to neutralize BMP-9 in the colon-26 mouse tumor model and, similar to soluble ALK1, it reduced the tumor burden in these mice due to its anti-angiogenesis properties." (PMID 24670474, 2014).
tumor (continued). "CD105 (endoglin) is a homodimeric transmembrane glycoprotein, a modulator of angiogenesis that marks the angiogenic tumor blood vessels but is not expressed by the normal preexisting mature large vessels." (PMID 23936513, 2013). "In contrast, TS/A tumors induced in BALB/c mice express higher levels of endoglin, indicating that the elevated endoglin level originate from the endothelial cells present in the tumor blood vessels rather than from the tumor cells themselves." (PMID 23593103, 2013). "In our study, a single treatment of tumors with m_siRNA 869 electrotransfer or multiple treatment with m_siRNA 869 alone were sufficient to silence endoglin for up to 60%, but this was not or only slightly reflected in the reduction of tumor growth." (PMID 23593103, 2013). "Endoglin is a transforming growth factor-β (TGF- β) co-receptor that participates in the activation of a signaling pathway that mediates endothelial cell proliferation and migration in angiogenic tumor vasculature." (PMID 23593103, 2013). "The results of Northern blot analysis showed that toxicarioside A inhibited endoglin expression in a dose-dependent manner in the HUVECs but not in the CT26 or LL/2 tumor cells." (PMID 23209720, 2012). "The fact that intermediate monocytes may express pro-angiogenic (and thus potentially pro-tumor) factors such as TIE2, endoglin or VEGFR-2 has prompted us to investigate a particular subset of intermediate monocytes, the CD14++CD16+TIE2+ TEMs." (PMID 22973451, 2012). "These in vitro and in vivo results suggest that toxicarioside A treatment can significantly inhibit endoglin expression in tumor angiogenesis-related cells, such as HUVECs, but not in tumor cells (CT26 and LL/2)." (PMID 23209720, 2012). "Due to the role of endoglin in TGF-β signaling and decreased expression of endoglin in toxicarioside-A-treated HUVECs and TGF-β in the toxicarioside-A-treated CT26 and LL/2 tumor cells, we explored the roles played by endoglin and TGF-β in Smad signaling in HUVECs." (PMID 23209720, 2012). "Thus, we reasoned that endoglin (ENG)/CD105, which interacts with receptor complexes of the TGF‐β superfamily, may regulate TGF‐β signaling activation and tumor‐promoting traits in myCAFs." (PMID 40644310, 2025). "However, whether ENG contributes to TGF‐β signaling activation and tumor progression in human breast myCAFs has yet to be addressed." (PMID 40644310, 2025). "However, whether ENG expression mediates TGF‐β signaling activation and tumor‐promoting abilities in myCAFs remained unclear." (PMID 40644310, 2025). "Of note, cooperation between all three receptors and VEGF-A may also characterize malignant states, since NRP1, VEGFR2, ENG and VEGF-A are overexpressed in cancer;4,77–86 this was shown to be prominent in angiogenesis, which has a key role in tumor formation and development." (PMID 38242992, 2024). "The normalization of MCAM, VE-cadherin, and Endoglin expression by CBD supports the anti-angiogenic and anti-proliferative effect of CBD that has been described in vitro for HUVECs, but also in vivo, such as vascularization models in MatrigelTM sponges and reduction of tumor angiogenesis." (PMID 39518030, 2024). "The attenuating effect of CBD on MCAM, VE-cadherin, and Endoglin expression and its capacity to increase CD34+ ECs could therefore be a contributory factor in the anti-angiogenic anti-tumor effect described for CBD, while also increasing CD34+ endothelial progenitor cell-mediated repair." (PMID 39518030, 2024). "Notably, endoglin (CD105), an accessory receptor for transforming growth factor beta (TGF-β), has been shown to be overexpressed in vascular endothelial cells of tissues undergoing active angiogenesis such as regenerating and inflamed tissues or tumours." (PMID 37052868, 2023).